LYRM1 (LYR motif containing 1)
Description:
May promote cell proliferation and inhibition of apoptosis of preadipocytes.
Synonyms: A211C6.1
Tractability: PROTAC: its protein half-life has been measured.
Gene: Protein-coding gene on chromosome 16 (20,899,821 to 20,925,011, forward strand). Ensembl gene ENSG00000102897.
Subcellular location: Nucleus
Subcellular location (Human Protein Atlas): Nucleoplasm; Midbody
Gene Ontology:
Cellular component: mitochondrion; nucleoplasm; nucleus
Genetic constraint (gnomAD): Loss-of-function variants: 5 observed, 6.81 expected, observed/expected ratio (o/e) 0.73, 90% interval 0.38 to 1.51. That is too few expected variants to judge how well the gene tolerates losing a copy. Missense variants: 73 observed, 70.01 expected, observed/expected ratio (o/e) 1.04, 90% interval 0.86 to 1.27. Synonymous variants: 17 observed, 27.18 expected, observed/expected ratio (o/e) 0.63, 90% interval 0.43 to 0.94.
Homologues: Orthologues: chimpanzee LYRM1 (100% identical), macaque LYRM1 (99% identical), rabbit LYRM1 (94% identical), dog LYRM1 (93% identical), pig LYRM1 (93% identical), guinea pig LYRM1 (90% identical), rat Lyrm1 (90% identical), mouse Lyrm1 (88% identical), tropical clawed frog lyrm1 (66% identical), zebrafish lyrm1 (57% identical).
Diseases named in the same sentence as LYRM1 in open-access papers:
LYRM1 is named in the same sentence as 4 diseases in open-access papers, as found by Europe PMC text mining. Sharing a sentence is not in itself a finding about the gene and the disease. The quoted sentences say what the papers report.
Insulin resistance (2 papers, 2012 to 2023). Increased resistance towards insulin, that is, diminished effectiveness of insulin in reducing blood glucose levels. "To elucidate the mechanisms by which LYRM1 is involved in the pathogenesis of obesity-associated insulin resistance, we characterized how this gene is regulated by factors that modulate insulin sensitivity." (PMID 22110480, 2012). "The upregulation or downregulation of LYRM1 expression may be strongly linked to FFA or rosiglitazone-related insulin resistance." (PMID 22110480, 2012). "Our findings indicate that LYRM1 may be a new candidate gene related to obesity-associated insulin resistance." (PMID 22110480, 2012). "LYRM1 is a recently discovered gene that is involved in obesity-associated insulin resistance." (PMID 22110480, 2012). "In this study, we show that LYRM1 is a novel gene related to obesity-associated insulin resistance." (PMID 22110480, 2012). "Currently, we suggest that TNF-α-induced insulin resistance is only indirectly involved in increased LYRM1 expression." (PMID 22110480, 2012). "LYRM1 may be an important mediator in the development of obesity-related insulin resistance." (PMID 22110480, 2012). "LYR motif containing 1 (LYRM1) is a novel gene that is abundantly expressed in the adipose tissue of obese subjects and is involved in insulin resistance." (PMID 22110480, 2012).
Obesity (2 papers, 2012 to 2025). Accumulation of substantial excess body fat. "We hypothesize that these factors (FFAs, TNF-α, and resistin) and drug (rosiglitazone) may have a potential regulatory mechanism in obesity through the regulation of LYRM1 mRNA expression, thereby affecting insulin sensitivity." (PMID 22110480, 2012).
LYRM1 also shares sentences with these, for which no sentence is quoted: pancreatic cancer (3 papers); embryonic carcinoma (1).